KDM4A (lysine demethylase 4A)
Description:
Histone demethylase that specifically demethylates 'Lys-9' and 'Lys-36' residues of histone H3, thereby playing a central role in histone code. Does not demethylate histone H3 'Lys-4', H3 'Lys-27' nor H4 'Lys-20'. Demethylates trimethylated H3 'Lys-9' and H3 'Lys-36' residue, while it has no activity on mono- and dimethylated residues. Demethylation of Lys residue generates formaldehyde and succinate. Also able to demethylate histone H1-4 methylated at 'Lys-26' (H1.4K26me1, H1.4K26me2 and H1.4K26me3). Participates in transcriptional repression of ASCL2 and E2F-responsive promoters via the recruitment of histone deacetylases and NCOR1, respectively. [Isoform 2]: Crucial for muscle differentiation, promotes transcriptional activation of the Myog gene by directing the removal of repressive chromatin marks at its promoter. Lacks the N-terminal demethylase domain.
Synonyms: JHDM3A; JMJD2; JMJD2A; KIAA0677; TDRD14A
Tractability: Small molecule: a structure with a bound ligand is known; a high-quality ligand is known; it has a high-quality binding pocket; it belongs to a druggable protein family. PROTAC: UniProt records ubiquitination sites on it; ubiquitination databases record sites on it; a small molecule that binds it is known.
Target class: Epigenetic regulator; Jumonji domain-containing; Eraser; Lysine demethylase
Chemical probes: IOX1 (high quality), ML324
Gene: Protein-coding gene on chromosome 1 (43,649,256 to 43,705,518, forward strand). Ensembl gene ENSG00000066135.
Subcellular location: Nucleus
Subcellular location (Human Protein Atlas): Nucleoli fibrillar center; Nucleoplasm
Pathways (Reactome):
Chromatin organization: HDMs demethylate histones
DNA Repair: Recruitment and ATM-mediated phosphorylation of repair and signaling proteins at DNA double strand breaks
Signal Transduction: NR1H3 & NR1H2 regulate gene expression linked to cholesterol transport and efflux
Gene Ontology:
Molecular function: histone H3K36 demethylase activity; histone H3K36me2/H3K36me3 demethylase activity; histone H3K9me2/H3K9me3 demethylase activity; histone H4K20me2 reader activity; protein binding; ubiquitin protein ligase binding; zinc ion binding; histone demethylase activity; histone H3K9 demethylase activity
Biological process: negative regulation of autophagy; negative regulation of DNA-templated transcription; negative regulation of gene expression; chromatin organization; chromatin remodeling
Cellular component: fibrillar center; nucleoplasm; nucleus; chromatin; pericentric heterochromatin
Genetic constraint (gnomAD): Loss-of-function variants: 23 observed, 126.53 expected, observed/expected ratio (o/e) 0.18, 90% interval 0.13 to 0.26. The upper end of that interval is the gene's LOEUF score, 0.26, which puts it in group 1 of 6, group 1 being the genes least tolerant of losing a copy. Missense variants: 879 observed, 1,370.3 expected, observed/expected ratio (o/e) 0.64, 90% interval 0.61 to 0.68. Synonymous variants: 436 observed, 484.84 expected, observed/expected ratio (o/e) 0.9, 90% interval 0.83 to 0.97.
Homologues: Orthologues: chimpanzee KDM4A (99% identical), macaque KDM4A (99% identical), dog KDM4A (96% identical), rabbit KDM4A (96% identical), pig KDM4A (95% identical), mouse Kdm4a (94% identical), rat Kdm4a (93% identical), tropical clawed frog kdm4a (70% identical), Drosophila melanogaster Kdm5 (17% identical), Caenorhabditis elegans rbr-2 (15% identical). Paralogues in human: KDM4C (52% identical), KDM4B (49% identical), KDM4D (24% identical), KDM4F (24% identical), KDM4E (23% identical), KDM5B (20% identical), KDM5A (19% identical), KDM5C (19% identical), KDM5D (19% identical), JARID2 (9% identical).
Diseases named in the same sentence as KDM4A in open-access papers:
KDM4A is named in the same sentence as 100 diseases in open-access papers, as found by Europe PMC text mining. Sharing a sentence is not in itself a finding about the gene and the disease. The quoted sentences say what the papers report.
breast carcinoma (37 papers, 2011 to 2025). "It has also been reported that the inhibition or downregulation of KDM4A causes a decrease in the proliferation of acute myeloid leukemia, breast cancer, and prostate cancer." (PMID 35480330, 2022). "Breast cancer is associated with multiple histone demethylases, including KDM4A, KDM4B, and KDM4C." (PMID 40006021, 2025). "In MCF7 breast cancer cells, the downregulation of KDM4A by epi-editing alone induced a substantial inhibition in proliferation at 72 h and 96 h compared to control cells and to cells transfected with only CRISPRoff." (PMID 40537846, 2025). "KDM4A enhances breast cancer growth and metastasis via activating the Notch1-NICD-dependent signaling pathway." (PMID 40006021, 2025). "In breast cancer, KDM4A was shown to promote xenograft tumor growth and stimulate lung metastases in experimental mice." (PMID 40940894, 2025). "KDM4A can, for example, form a complex with ERα, inducing ERα-mediated transcription in breast cancer." (PMID 40537846, 2025). "Like in breast cancer cells, the knockdown of KDM4A in multiple colorectal cancer cell lines led to reduced cell proliferation, further increased apoptosis, and delayed G2−M phase progression of the cell cycle." (PMID 39620228, 2024). "KDM4A is overexpressed in ∼60% of patients with breast cancers and forms distinct expression profiles with other KDM4s among different BC subtypes." (PMID 37692513, 2023). "KDM4/KDM4A inhibitors such as NCDM-32B, JmjN peptide, Purpurogallin (9bf), PKF118–310, and ML324 cause inhibition of tumor cell proliferation in breast cancer, and showcase antiproliferative activity in prostate cancer." (PMID 37218871, 2023). "JIB-04, the most advanced preclinical KDM4 inhibitor, inhibits growth and lowers tumor burden in non-small cell lung cancer and breast cancer, both in vitro and animals, and targets KDM4A, KDM4B, and KDM4E." (PMID 37218871, 2023). "This study investigates the mechanism of hsa_circ_0001429 adsorbing miR-205 and regulating the expression of KDM4A to promote breast cancer metastasis and its mechanism." (PMID 35833065, 2022). "For instance, KDM4A is overexpressed and sometimes amplified in several neoplasms such as leukemia, lung, prostate, colorectal, and breast cancer." (PMID 35480330, 2022). "Inhibiting KDM4A blocks breast cancer stem-like cells proliferation used as therapy for resistant cancer stem-like cells." (PMID 34011940, 2021). "KDM4A is overexpressed in breast cancer and KDM4A knockdown inhibited cell proliferation, migration and invasion." (PMID 34220955, 2021). "Taken together, KDM4A seems to play an important role in SP1 downregulation in advanced breast cancer cells." (PMID 29651880, 2018). "This confirms the oncogenic role of KDM4A in colon and breast cancer." (PMID 40537846, 2025). "Additionally, the expression levels of FYN and KDM4A were found to be correlated with poor prognosis in a previously reported breast cancer cohort, highlighting the potential of targeting these two genes as therapeutic targets for TNBC." (PMID 40243589, 2025). "Indeed, KDM4A knockdown in MCF-7 breast cancer cells resulted in the reduction of oncogenic properties." (PMID 40537846, 2025). "Therefore, depletion of KDM4A in ER-positive T47D breast cancer cells reduces the expression of ER target genes (such as the oncogenes c-Jun and Cyclin D1) and leads to decreased cell growth." (PMID 39620228, 2024). "Some studies have reported that KDM4A may act as a new breast cancer inhibitor, which can inhibit the development of breast cancer by inducing apoptosis of breast cancer cells." (PMID 35833065, 2022). "Other JmjC KDMs involved in breast cancer are KDM4A, KDM4B and, KDM4C." (PMID 36185256, 2022). "Several studies have reported that KDM4A is highly expressed in breast cancer tissues." (PMID 29682202, 2018). "KDM4A is overexpressed in several types of cancer, including breast cancer." (PMID 29682202, 2018).
breast carcinoma (continued). "Following this validation of the sgRNA-KDM4A with CRISPRoff to downregulate KDM4A in HEK293T cells, the efficacy was explored in HCT116 colon and MCF7 breast cancer cells." (PMID 40537846, 2025). "Various studies have shown that KDM4A/JMJD2A, KDM4B/JMJD2B, and/or KDM4C/JMJD2C are overexpressed in breast cancer, colorectal cancer, lung cancer, prostate cancer, and other tumors and are essential for the efficient growth of cancer cells." (PMID 39620228, 2024). "Compound 16, a methylated derivative of compound 15, has similar in vitro inhibitory activities against KDM4A and KDM4C but improved anti-proliferative and anti-transformation activities against breast cancer cells." (PMID 37692513, 2023). "The level of H3K9me3 in cells depended on histone lysine methyltransferases or the opposing demethylases, and various studies have shown that the demethylases KDM4A/JMJD2A, KDM4B/JMJD2B and/or KDM4C/JMJD2C are overexpressed in breast cancer." (PMID 36303253, 2022). "Increased levels of KDM4A and KDM4B have been observed in ERα positive breast cancer cells, while TNBC cells showed an increased level of KDM4C." (PMID 36185256, 2022). "The most advanced preclinical KDM4 inhibitor is JIB-04 which targets KDM4A, KDM4B, and KDM4E and can inhibit growth and reduce tumor burden in non-small cell lung cancer (NSCLC) and breast cancer in vitro and in vivo." (PMID 34220955, 2021). "This molecule strongly inhibited KDM4A in in vitro assays with an IC50 of 24.37 and 10.1 μM, and in breast cancer cells increased the levels of H3K9me3 and H3K36me3, specific targets of KDM4A, already after 24 h of treatment at 10 μM." (PMID 32523934, 2020). "KDM4A is down-regulated in bladder cancer, and KDM4A and KDM4B are up-regulated in breast cancer and peripheral nerve sheath tumours respectively." (PMID 25145438, 2014). "For example, basal breast cancer cells significantly overexpress KDM4A and D. In contrast, infiltrating duct carcinoma tends to exhibit high KDM4A levels, but fibroadenoma does not." (PMID 37067993, 2023). "For example, KDM4A and KDM4D are co-overexpressed in basal breast cancer, while the KDM4A level is higher in infiltrating breast duct carcinoma (IBDC) than in breast fibroadenoma, and KDM4B is overexpressed in both estrogen receptor (ER)-positive breast cancer and triple-negative breast cancer." (PMID 37692513, 2023). "Since its discovery and initial characterization, JIB-04 has been used as an inhibitor of the H3K9/K36 demethylase activity of KDM4A in leukemia, the H3K9 demethylase activity of KDM3B in lung cancer, and the H3K4 demethylase activity of members of the KDM5 family in breast cancer and glioblastoma." (PMID 30237855, 2018). "Remarkably, expression of KDM4A, the most abundantly expressed gene among KDM4 demethylases in TNBC cell lines was enriched in TNBC compared to other breast cancer subtypes and was positively correlated with FYN expression in CCLE database, suggesting that KDM4 regulates FYN mRNA levels." (PMID 40243589, 2025). "Several reports indicate that KDM4 family members are over-expressed in various cancers: KDM4A, KDM4B, and KDM4C are over-expressed in prostate cancer; amplification of KDM4B is shown in medulloblastoma; and KDM4C is required for the growth of breast carcinoma and diffuse large B cell lymphoma." (PMID 36975603, 2023). "Mammary epithelial cells MCF-10A and human breast cancer cell lines BT474, SKBr-3, ZR-75-30, and MCF7 are cultured, and the mRNA expressions of hsa_circ_000 1429, miR-205, and KDM4A are detected by qRT-PCR; hsa_circ_000 1429 binds to miR-205, and miR-205 targets KDM4A." (PMID 35833065, 2022). "Downregulation of two other KDM4 family members, KDM4A or KDM4B, did not affect the growth of the cell line tested, confirming the specific requirement for KDM4C in basal breast cancer." (PMID 40457074, 2025).
prostate carcinoma (24 papers, 2011 to 2026). A carcinoma that arises from epithelial cells of the prostate gland. "Furthermore, KDM4A was implicated in the regulation of androgen receptor (AR) expression in prostate cancer cells by the epigenetic modulation of AR enhancer." (PMID 40940894, 2025). "KDM4A promoted docetaxel resistance in castration-resistant prostate cancer (C-R PC) cell lines by regulating cytoskeleton remodeling through miR-34a/Stathmin 1/β3-Tubulin axis." (PMID 40940894, 2025). "In breast and prostate cancers, KDM4A forms a complex with estrogen and androgen receptors and activates downstream target genes." (PMID 39620228, 2024). "The histone demethylase JMJD2A/KDM4A facilitates prostate cancer development, yet how JMJD2A function is regulated has remained elusive." (PMID 37870957, 2023). "The Jumonji C-containing histone lysine demethylase family 4 (KDM4) members, KDM4A‒KDM4C, serve as critical coactivators of AR to promote tumor growth in prostate cancer and are candidate therapeutic targets to overcome AR mutations/alterations-mediated resistance in CRPC." (PMID 35534851, 2022). "Importantly, we have shown that myricetin which targets KDM4A − C curbs tumor growth in C4-2B xenografts, suggesting an anti-cancer agent in prostate cancer." (PMID 35534851, 2022). "KDM4A recruits E2F1 to control cancer metabolism for proficient prostate cancer growth." (PMID 30683841, 2019). "The histone lysine demethylase KDM4A serves as a coactivator for E2F1, binding to the promoters of PDK1 and PDK3, thus influencing the metabolic transition between glycolysis and mitochondrial oxidation in prostate cancer." (PMID 41158756, 2026). "Interestingly downstream gene targets of prostate cancer cell lines treated with 11 showed a number of pathways alongside 27% androgen response gene targets identifying a possible crossover function of LSD1 and KDM4A/B." (PMID 31428579, 2019).
cardiac hypertrophy (16 papers, 2013 to 2023). "KDM3A is a demethylase of H3K9me2 residues with a similar effect on the production of cardiac hypertrophy to that detected with KDM4A." (PMID 36523510, 2022). "Although cardiac-specific Kdm4a deficient mice and transgenic mice which overexpress Kdm4a show no overt baseline phenotype, when subjected to pressure overload, inactivation of Kdm4a attenuates hypertrophic response while Kdm4a overexpression enhances cardiac hypertrophy." (PMID 25408700, 2014). "Four-and-a-half LIM domain 1 (FHL1) is a key component of the mechano-transducer machinery in the heart, and KDM4A can occupy the FHL1 promoter in response to transverse aortic constriction and up-regulate FHL1 levels by removing methyl groups from H3K9me3 during cardiac hypertrophy." (PMID 37692513, 2023).
lung carcinoma (14 papers, 2014 to 2025). "Taken together, these studies suggest that KDM4A promotes lung cancer progression by reducing the tumor suppressor CHD5 and activating related oncogenes." (PMID 37692513, 2023). "A study on lung cancer has shown that lysine demethylase 4A (KDM4A) increases the transcriptional activity of DLX5 by promoting the demethylation of DLX5." (PMID 34409024, 2021). "JMJD6 and KDM4A might serve as biomarkers for lung cancer although further mechanistic investigations were necessary." (PMID 30002791, 2018). "Analysis of previously published RNA sequencing data from a series of osimertinib tolerant EGFR mutated lung cancer cell lines revealed higher expression levels of FYN and KDM4A in the drug persisters, but not SRC." (PMID 40243589, 2025). "Treatment with microRNA inhibitors in neuroblastoma (SK-N-AS cells) and lung cancer cells (H2591) also increased KDM4A protein levels and promoted copy gain of 1q12h but not chromosome 8 centromere." (PMID 26755726, 2016).
osteosarcoma (13 papers, 2011 to 2024). A usually aggressive malignant bone-forming mesenchymal neoplasm, predominantly affecting adolescents and young adults. "For example, lysine demethylase 4A (KDM4A) protected against ferroptosis by decreasing H3K9me3 abundance at the SLC7A11 promoter to upregulate the expression of SLC7A11 in osteosarcoma." (PMID 37229485, 2023). "Moreover, decreased KDM4A expression resulted in increased cell ferroptosis, attenuated migration ability, and enhanced cisplatin sensitivity in osteosarcoma 143B and HOS cells." (PMID 36819098, 2023). "KDM4A depletion was reported to promote cell ferroptosis in osteosarcoma." (PMID 35287356, 2022). "KDM4A-regulated SLC7A11 decreases ferroptosis of osteosarcoma cells." (PMID 34177591, 2021). "KDM4A expression was significantly upregulated in OS tumor tissues relative to normal tissues, while KDM4A knockdown promoted ferroptosis in osteosarcoma cells, limited pulmonary metastasis of osteosarcoma, and could act synergistically with cisplatin." (PMID 35837104, 2022). "For instance, lysine demethylase 4A (KDM4A) reduces the levels of H3K9me3 at the SLC7A11 promoter, leading to increased expression of SLC7A11 in osteosarcoma." (PMID 39595619, 2024). "In addition, KDM4A, a histone demethylase with the function of demethylating H3K9me3 in the promoter region of SLC7A11, inhibited ferroptosis-related cell death in osteosarcoma." (PMID 36819098, 2023).
bladder cancer (12 papers, 2011 to 2025). "In summary, our findings suggest that KDM4A, as a druggable epigenetic regulator, holds potential as a novel target for assessing malignancy risk and developing new therapeutic strategies for bladder cancer." (PMID 39461328, 2024). "In accordance, a positive correlation between USP7 and KDM4A protein expression was noted in bladder cancer clinical samples." (PMID 41429764, 2025). "Functional validation tests confirmed that USP7 and KDM4A act complementarily to drive bladder cancer cell proliferation." (PMID 41429764, 2025). "Our findings highlighted Sqle's critical role in mediating the antitumor effect of Kdm4a inhibition in bladder cancer." (PMID 39461328, 2024). "In our screening for antitumor agents in bladder cancer, we identified the KDM4A inhibitor ML324 as a potent candidate." (PMID 39461328, 2024). "In this study, we observed transcriptional changes following Kdm4a knockout in bladder cancer organoids, primarily characterized by impaired cholesterol synthesis and increased apoptosis." (PMID 39461328, 2024). "Conversely, genomic loss of KMD4A and concomitant decrease in mRNA levels has also been reported in multiple tumour types 45, particularly bladder cancer where KDM4A downregulation correlates with tumour progression." (PMID 27624942, 2016). "Tissue culture and animal tests showed that KDM4A pis ro-proliferative in bladder cancer cells." (PMID 41429764, 2025). "●The KDM4A-SQLE-JNK/c-Jun axis is consistently observed in bladder cancer PDX models." (PMID 39461328, 2024). "Essentially, ML324 could impede the growth of bladder cancer by targeting Kdm4a." (PMID 39461328, 2024). "Therefore, KDM4A or PHRF1 may be potential novel targets for the treatment of bladder cancer." (PMID 41215711, 2025). "Our findings reveal the presence of a Kdm4a-Sqle-ROS-JNK/c-Jun signaling axis that regulates oxidative stress balance, offering a novel strategy for targeted therapy in bladder cancer." (PMID 39461328, 2024). "The inhibition of Kdm4a, resulting in the downregulation of Sqle and subsequent suppression of ROS/JNK/c-Jun signaling pathway, has been clearly elucidated in mouse bladder cancer models." (PMID 39461328, 2024). "Overall, we identified the KDM4A inhibitor ML324, which demonstrated a potent cytotoxic effect on both human and mouse bladder cancer models." (PMID 39461328, 2024). "KDM4A can assemble into a complex with LSD1 and promote muscle invasion, extravesical extension, and lymph node metastasis of bladder cancer." (PMID 37692513, 2023). "The roles of KDM4 family members, including KDM4A, KDM4B, KDM4C and KDM4D, on bladder cancer remains unclear." (PMID 39461328, 2024). "Thus, to clarify the role of KDM4 on the growth inhibition of bladder cancer organoids, control and knockout groups were established by transducing organoids with lentiviral vectors expressing either non-targeting control (scramble) or sgRNAs targeting Kdm4a/b/c/d, respectively." (PMID 39461328, 2024).